MIR497HG (mir-497-195 cluster host gene)
Synonyms: MIR195HG; ALOX12-AS1
Gene: Long non-coding RNA gene on chromosome 17 (6,875,220 to 7,022,133, reverse strand). Ensembl gene ENSG00000267532.
Diseases named in the same sentence as MIR497HG in open-access papers:
MIR497HG is named in the same sentence as 5 diseases in open-access papers, as found by Europe PMC text mining. Sharing a sentence is not in itself a finding about the gene and the disease. The quoted sentences say what the papers report.
breast carcinoma (3 papers, 2022 to 2024). "Additionally, MIR497HG was reported to be associated with proliferation, migration, invasion, and lymph node metastasis in bladder cancer and breast cancer." (PMID 35174152, 2022). "In our study, MIR497HG was observed to be negatively correlated with tumor size, lymphocyte metastasis, and TNM staging in breast cancer patients via Chi-square test, and downregulated expression of MIR497HG was evaluated by RT-qPCR." (PMID 38956558, 2024). "MIR497HG targets miR-16-5p and exerts negative regulation, and upregulated MIR497HG expression plays an inhibitory role in breast cancer." (PMID 38956558, 2024). "In general, MIR497HG was decreased in breast cancer, and the MIR497HG/miR-16-5p axis regulated breast cancer tumorigenesis, providing effective insights for the diagnosis of patients." (PMID 38956558, 2024). "We propose that MIR497HG can serve as a prognostic factor for tamoxifen sensitivity in patients with ER+ breast cancer." (PMID 36815359, 2023). "The findings reveal that ZEB1‐induced MIR497HG depletion contributes to breast cancer progression and tamoxifen resistance through PI3K‐AKT signaling." (PMID 36815359, 2023). "In conclusion, overexpression of MIR497HG blocked the biological activity of breast cancer cells." (PMID 38956558, 2024). "Their host gene, MIR497HG, was also downregulated in breast cancer sample." (PMID 36815359, 2023). "Therefore, MIR497HG was identified as a critical regulator of the signaling cross‐talk between ERα and PI3K‐AKT in ER+ breast cancer." (PMID 36815359, 2023). "The derivatives of MIR497HG, miR‐497, and miR‐195, work together to inhibit PI3K‐AKT signaling by downregulating the five positive regulators of PI3K‐AKT signaling, indicating MIR497HG can serve as a prognostic factor for tamoxifen sensitivity in patients with ER+ breast cancer." (PMID 36815359, 2023).
bladder urothelial carcinoma (1 paper, 2020). "Furthermore, we analyzed The Cancer Genome Atlas (TCGA) bladder urothelial carcinoma RNA sequencing data and revealed that the expression levels of miR-497 and miR-195 were inhibited in various stage of BCa, and these data also showed that MIR497HG was downregulated in BCa." (PMID 33363213, 2020).
tumor (2 papers, 2020 to 2024). "MIR497HG is a potential and exploitable tumor suppressor gene on chromosome 17p13.1." (PMID 38956558, 2024). "Thus, MIR497HG was regarded as a tumor suppressor gene in BCa." (PMID 33363213, 2020).
MIR497HG also shares sentences with these, for which no sentence is quoted: bladder cancer (1 paper); colorectal cancer (1).